CD3G (CD3 gamma subunit of T-cell receptor complex)
Description:
Part of the TCR-CD3 complex present on T-lymphocyte cell surface that plays an essential role in adaptive immune response. When antigen presenting cells (APCs) activate T-cell receptor (TCR), TCR-mediated signals are transmitted across the cell membrane by the CD3 chains CD3D, CD3E, CD3G and CD247/CD3Z. All CD3 chains contain immunoreceptor tyrosine-based activation motifs (ITAMs) in their cytoplasmic domain. Upon TCR engagement, these motifs become phosphorylated by Src family protein tyrosine kinases LCK and FYN, resulting in the activation of downstream signaling pathways. In addition to this role of signal transduction in T-cell activation, CD3G plays an essential role in the dynamic regulation of TCR expression at the cell surface. Indeed, constitutive TCR cycling is dependent on the di-leucine-based (diL) receptor-sorting motif present in CD3G.
Synonyms: T3G; CD3-GAMMA; CD3GAMMA; IMD17
Tractability: Small molecule: a structure with a bound ligand is known. Antibody: an approved drug acts on it; UniProt places it where antibodies can reach, with high confidence; its Gene Ontology location is reachable by antibodies, with high confidence; UniProt predicts a signal peptide or a membrane-spanning region; the Human Protein Atlas places it where antibodies can reach. PROTAC: ubiquitination databases record sites on it.
Gene: Protein-coding gene on chromosome 11 (118,344,344 to 118,355,161, forward strand). Ensembl gene ENSG00000160654.
Subcellular location: Cell membrane
Subcellular location (Human Protein Atlas): Cytosol; Plasma membrane
Pathways (Reactome):
Immune System: Co-inhibition by PD-1; Downstream TCR signaling; FCGR activation; Generation of second messenger molecules; Immunoregulatory interactions between a Lymphoid and a non-Lymphoid cell; Phosphorylation of CD3 and TCR zeta chains; Regulation of actin dynamics for phagocytic cup formation; Role of phospholipids in phagocytosis; Translocation of ZAP-70 to Immunological synapse
Disease: FCGR3A-mediated IL10 synthesis; FCGR3A-mediated phagocytosis
Vesicle-mediated transport: Cargo recognition for clathrin-mediated endocytosis; Clathrin-mediated endocytosis
Gene Ontology:
Molecular function: identical protein binding; MHC class II receptor activity; protein binding; transmembrane signaling receptor activity; signaling receptor complex adaptor activity; T cell receptor binding
Biological process: cell surface receptor signaling pathway; establishment or maintenance of cell polarity; protein transport; regulation of lymphocyte apoptotic process; T cell receptor signaling pathway; adaptive immune response; alpha-beta T cell activation; gamma-delta T cell activation; positive thymic T cell selection; protein-containing complex assembly; T cell activation
Cellular component: alpha-beta T cell receptor complex; plasma membrane; clathrin-coated endocytic vesicle membrane; external side of plasma membrane; gamma-delta T cell receptor complex; membrane
Genetic constraint (gnomAD): Loss-of-function variants: 21 observed, 25.39 expected, observed/expected ratio (o/e) 0.83, 90% interval 0.59 to 1.19. The upper end of that interval is the gene's LOEUF score, 1.19, which puts it in group 5 of 6, group 1 being the genes least tolerant of losing a copy. Missense variants: 206 observed, 211.4 expected, observed/expected ratio (o/e) 0.97, 90% interval 0.87 to 1.09. Synonymous variants: 71 observed, 76.04 expected, observed/expected ratio (o/e) 0.93, 90% interval 0.77 to 1.14.
Gene-disease validity (ClinGen):
ClinGen rates the evidence that CD3G causes each of these diseases.
combined immunodeficiency due to CD3gamma deficiency (autosomal recessive): Definitive.
Homologues: Orthologues: chimpanzee CD3G (100% identical), macaque CD3G (82% identical), rat Cd3g (71% identical), guinea pig CD3G (70% identical), mouse Cd3g (70% identical), dog CD3G (69% identical), pig CD3G (42% identical), tropical clawed frog cd3g (34% identical). Paralogues in human: CD3D (37% identical), CD3E (27% identical).
Diseases named in the same sentence as CD3G in open-access papers:
CD3G is named in the same sentence as 85 diseases in open-access papers, as found by Europe PMC text mining. Sharing a sentence is not in itself a finding about the gene and the disease. The quoted sentences say what the papers report.
Immunodeficiency (11 papers, 2015 to 2025). Failure of the immune system to protect the body adequately from infection, due to the absence or insufficiency of some component process or substance. "Crucially, scRNA‐seq resolved these population‐level associations to specific T‐cell subpopulations, revealing CD3G downregulation in naïve T cells as a key mediator of post‐ischemic immune dysfunction." (PMID 40702735, 2025). "A PubMed search using the keywords “CD3G mutation” and “immunodeficiency” revealed reports of seven patients of Turkish descent and two of Spanish descent from five unrelated families (three with consanguinity)." (PMID 31921117, 2019). "An elevation of TCRγδ T cells has been observed in some combined immunodeficiencies such as recombination activating gene 1,2 deficiency, CD3γ, and CD3δ, as a consequence of CMV infection or delayed-onset combined immune deficiency with granuloma and/or autoimmunity." (PMID 28747912, 2017). "CD3γ deficiency, in contrast with other CD3 immunodeficiencies, allows in humans for the selection of substantial numbers of polyclonal peripheral T cells, which expressed low levels of (at least partially) functional TCR complexes." (PMID 36119034, 2022). "Despite the high sequence homology between CD3γ and CD3δ, the clinical consequences of the corresponding immunodeficiencies (ID) in humans are very different (mild and severe, respectively), and mouse models do not recapitulate findings in human ID." (PMID 34249896, 2021). "Humans lacking CD3γ (γ—) show reduced surface TCR expression levels associated to a potentially lethal immunodeficiency and/or autoimmunity of variable severity." (PMID 36119034, 2022). "Moreover, Cd3g is closely related to the surface protein CD3 in T cells and a deficiency of Cd3g leads to immunodeficiency." (PMID 34180954, 2021). "CD3γ deficiency, unlike CD3 δ, ε, and ζ deficiency, tends to present as combined immunodeficiency with variable onset." (PMID 27222657, 2016).
Autoimmunity (9 papers, 2017 to 2025). The occurrence of an immune reaction against the organism's own cells or tissues. "CD3γ deficiency offers another illustrative example of how defect in central tolerance can drive autoimmunity." (PMID 41394846, 2025). "Recently, one study showed that T-cells in the CD3G-deficient patients had reduced diversity, reduced suppressive function, and increased clonality in autoimmunity." (PMID 36176400, 2022). "Aside from mutations in CD3ζ, CD3γ mutations can also result in a range of phenotypes including mild immunodeficiency to autoimmunity." (PMID 34012443, 2021). "Distinct from the previously reported CD3G mutations, which mainly present as autoimmunity, the novel CD3G deletion (c.del213A) in our patient caused an obvious decrease in switched memory B cells and diminished CD40L expression." (PMID 31921117, 2019). "However, CD3G mutations alone lead to a less severe condition, which is mainly characterized by autoimmunity." (PMID 31921117, 2019). "Among these, CD3G encodes the CD3-gamma polypeptide, which plays an important role in autoimmunity." (PMID 36761165, 2022). "Our patient with the novel CD3G mutation presented with predominant B-cell deficiency overlapping with the CVID phenotype but without recognizable autoimmunity, which was consistent with his normal Treg suppression function." (PMID 31921117, 2019). "Taken together, the patients with CD3G mutations were characterized by predominant B-cell deficiency and autoimmune hypothyroiditis, except for our CD3γDel213A patient, who did not develop autoimmune disorders." (PMID 31921117, 2019). "In conclusion, our patient had a novel CD3G gene deletion and presented with predominant B-cell deficiency and NRH, which mimicked the CVID phenotype but without the occurrence of autoimmune disorders; this was consistent with his normal number of Treg cells and his normal suppression function." (PMID 31921117, 2019).
melanoma (6 papers, 2016 to 2023). A malignant, usually aggressive tumor composed of atypical, neoplastic melanocytes. "We observed positive correlations between three types of NLS and T-cell receptor-associated gene expression signatures, such as CD8A, CD3G, CCL5, TIGT, LCK and IKZF3 in lung cancers and primary melanomas after adjusting clinical factors." (PMID 37100920, 2023). "CCL5 expression in a murine model of spontaneous melanoma correlated with CD3γ expression and T cell recruitment, while increased level of CCR5, the receptor for CCL5, was associated with positive outcomes in melanoma models due to T cell retention in tumors." (PMID 30899263, 2019). "In addition to the purity check upon cell sorting, potential CTL contamination in melanoma cell samples isolated from the co-cultures was checked by including a series of CTL markers on the NanoString (CD3D, CD3E, CD3G, CD8A and CD8B)." (PMID 27625650, 2016). "In addition, the T cell markers Cd3g and Cd8a showed a trend towards higher expression in NRF2 knockout tumors and quantification of CD3 + immune cell infiltration into control and NRF2 knockout melanomas showed a similar trend." (PMID 32978520, 2020).
Sepsis (6 papers, 2020 to 2025). Sepsis is defined as life-threatening organ dysfunction caused by a dysregulated host response to infection. "Briefly, we constructed a comprehensive model for screening sepsis-related genes, confirming that FERNT3 and CD3G are DEGs in a mouse sepsis model." (PMID 38255822, 2024). "The results demonstrated a high correlation between the expression of CD3G and typical pro-inflammatory cytokines in the sepsis mice." (PMID 38255822, 2024). "To further validate the accuracy and potential of the hub genes FERMT3 and CD3G in sepsis diagnosis, we conducted correlation analysis between the expression of these genes in sepsis mice and the levels of typical inflammatory cytokine in vivo." (PMID 38255822, 2024). "This relationship was further confirmed in a sepsis mouse model, where the expression of CD3G in CLP sepsis mice was significantly decreased compared with the sham group." (PMID 38255822, 2024). "Future studies examining CD3G expression longitudinally across sepsis stages, and specifically within neonates with bacteremia who do or do not progress to shock, may help establish its value as a predictive biomarker of disease severity." (PMID 40927580, 2025). "Based on these results, it can be reasonably inferred that FERMT3 and CD3G may serve as potent biomarkers for specifically diagnosing and predicting the severity and progression of sepsis." (PMID 38255822, 2024). "The results indicated that both CD3G and FERMT3 play crucial roles in the immune system during sepsis." (PMID 38255822, 2024). "Our findings showed that the expression of RETN, S100A12, IL18R1, and KL was higher in the sepsis group, while the expression of GZMB, HLA-DPA1, CD3E, IL2RB, CD3G, and CCR3 was higher in the control group." (PMID 38124071, 2023). "CD3G is an upregulated gene involved in T cells and has been reported to be inversely correlated with sequential organ failure (SOFA) and mortality in sepsis." (PMID 36527479, 2023). "As shown in these figures, the expression levels of RETN, S100A12, IL18R1, and KL were higher in the sepsis group, while that of GZMB, HLA-DPA1, CD3E, IL2RB, CD3G, and CCR3 were higher in the normal group (p < 0.05)." (PMID 38124071, 2023). "Upregulated genes identified in sepsis Th17 cell compared to bacteraemia cells were involved in T cell differentiation (ITGA4 and CCR7; 0.80 and 0.41log2FC, respectively), activation, and antigen receptor signalling (CD3G; 0.98log2FC) pathways." (PMID 41208955, 2025). "The hypermethylation of the CD3G gene promoter in neonates with sepsis aligns with transcriptomic analyses showing decreased expression of CD3G in neonates with EOS compared to neonates without sepsis and in neonates with septic shock compared to neonates with bacteremia." (PMID 40927580, 2025). "Furthermore, the correlation between these hub genes and downstream cytokines in sepsis mice was substantiated, suggesting that FERMT3 and CD3G, as upstream molecules, may possess more stable characteristics for diagnosis compared with downstream cytokines." (PMID 38255822, 2024). "Neonates with sepsis show differential hypermethylation of the CD3G and CD3D gene promoters and hypomethylation of IL10 gene promoter compared to controls without sepsis." (PMID 40927580, 2025). "In our study, bioinformatics analysis identified a negative correlation between CD3G and the SOFA score, indicating severe dysfunction of T-cell immunodeficiency in severe sepsis patients with high SOFA scores." (PMID 38255822, 2024).
breast carcinoma (3 papers, 2017 to 2025). "In breast cancer and colorectal cancer, this gene has been confirmed to be differentially expressed compared to normal controls, implying that CD3G can distinguish breast cancer and colorectal cancer samples from other tumor subtypes and normal controls." (PMID 29152097, 2017). "More recently, two analyses of RNAseq of TI Treg cells reported the use of the ratios CCR8/FOXP3 for breast cancer and CCR8/CD3G for lung and colorectal cancers, which had a modest predictive value in terms of overall survival." (PMID 34599187, 2021).
cervical cancer (3 papers, 2022 to 2024). A primary or metastatic malignant neoplasm involving the cervix. "Several recent bioinformatics studies found that CD3G is closely associated with tumors, such as cervical cancer and triple-negative breast cancer, and with immune system alterations that occur during Sjögren’s disease." (PMID 38169604, 2023). "During the multi-step process of cervical cancer development, CD3G expression was significantly increased in CIN1 lesions compared to normal tissues." (PMID 36176400, 2022).
cervical squamous cell carcinoma (3 papers, 2019 to 2024). A squamous cell carcinoma arising from the cervical epithelium. "Compared to other histological types, CD3G had the highest expression in Cervical Squamous Cell Carcinoma (CSCC)." (PMID 36176400, 2022). "In silico studies in uterine cervical squamous cell carcinoma have suggested that elevated CD3G expression could be a novel immunotherapeutic biomarker." (PMID 38396726, 2024).
lung carcinoma (3 papers, 2013 to 2024). "The same is true also for the seventh intersected biomarker from our study, expression level of CD3G gene, which was found to be associated with better response to lung cancer in a recent report on a lower sampling, in line with the current findings." (PMID 39723204, 2024).
T-cell immunodeficiency (3 papers, 2021 to 2025). A broad classification of disorders that affect the cell-mediated aspect of the immune response. "CD3D mutations in T cells cause destructive immunity innate errors, while CD3G deletion leads to T cell immunodeficiency." (PMID 40697415, 2025). "Defects in CD3G are associated with T cell immunodeficiency, while CD3D is involved in T-cell development and signal transduction." (PMID 34367157, 2021).
asthma (2 papers, 2006 to 2022). "Further, to explore the potential function of key hub genes in childhood asthma, we used GSEA to analyze enriched KEGG pathways in the samples with high CD3D or CD3G expression in the different datasets." (PMID 36118895, 2022). "To date, no studies have reported on the relationship between CD3D, CD3G, RGS1, HLA-DMB, GBP4, GBP5, and asthma." (PMID 36118895, 2022).
autoimmune disease (2 papers, 2021 to 2023). A disorder resulting from loss of function or tissue destruction of an organ or multiple organs, arising from humoral or cellular immune responses of the individual to their own tissue constituents. "Down-regulation of CD3G can lead to compromised immune function, and may induce a variety of autoimmune diseases." (PMID 38169604, 2023).
COVID-19 (2 papers, 2023 to 2024). A disease caused by infection with severe acute respiratory syndrome coronavirus 2. "The results indicated six hub DEGs for comparison of T1DM and COVID-19 convalescence (CD3G, YES1, ALAS2, MYO1C, NCR3, PRKACB) and two hub DEGs for comparison of T2DM and COVID-19 convalescence (PTRF, EHD1)." (PMID 38169604, 2023). "We analyzed the relationship of immune cell infiltration with two hub DEGs (CD3G and YES1) in the T1DM and COVID-19 convalescence data, and with two other hub DEGs (PTRF and EHD1) in the T2DM and COVID-19 convalescence data." (PMID 38169604, 2023). "Forkhead-box C1 (FOXC1) is a TF that regulates the expression of CD3G and YES1, and may therefore affect the development of T1DM after COVID-19 convalescence." (PMID 38169604, 2023). "Of note, the immunoreceptor Tyr-based activation motifs (ITAMs) on CD3δ and CD3γ showed increased phosphorylation whereas the CD3ζ ITAMs showed a mixed phosphorylation pattern in the COV group, suggesting that TCR signaling is partially activated in the COVID-19 patients." (PMID 38389037, 2024).
hepatocellular carcinoma (2 papers, 2022 to 2024). A malignant tumor that arises from hepatocytes. "Key markers, such as PTPRC, CD3E, CD4, CD79A, and CD3G in immune cells, EPCAM and KRT19 in epithelial cells, and MME and PECAM1 in stromal cells, were identified, providing crucial insights into hepatocellular carcinoma progression and immune response mechanisms." (PMID 39388011, 2024).
IPEX syndrome (2 papers, 2021 to 2025). "While present in almost all categories, their burden and distribution vary, with certain defects acting as clear ‘hotspots’, such as IPEX syndrome, APECED, LRBA, RAG1, RAG2, CD3γ, Helios, ARPC1B, and CD55 deficiencies." (PMID 41394846, 2025).
leukemia (2 papers, 2019 to 2020). A malignant (clonal) hematologic disorder, involving hematopoietic stem cells and characterized by the presence of primitive or atypical myeloid or lymphoid cells in the bone marrow and the blood. "Each validated gene in this category, i.e., CD3G, DFFA, GIGYF1, GIGYF2, and INTS3 were shown to play a role in neoplastic processes, including leukemia." (PMID 31709175, 2019). "miR-494-3p was mainly paired with immune genes (CD3G, CXCL13, CXCR5, KLRC4), some of which had been annotated as oncogenes in leukemia including IGF1 (DRG; pan-cancer), IKZF3 (driver; leukemia), NABP1 (oncogene; leukemia), and PDGFRA (oncogene; pan-cancer)." (PMID 32605588, 2020).
lymph node metastases (2 papers, 2020 to 2022). "In addition, a previous study demonstrated a similar association of CD274 and CD3G considering lymph node metastases and hypermutation, respectively." (PMID 35204406, 2022).
Neonatal sepsis (2 papers, 2021 to 2025). Systemic inflammatory response to infection in newborn babies. "In summary, transcriptomic profiling has uncovered key immune pathways involved in neonatal sepsis, including T-cell receptor signaling (CD3G), leukocyte chemotaxis (CXCL10, CSK), inflammatory activation (MM8, NF-κB1A), and IFN-1-mediated immune modulation." (PMID 40927580, 2025). "Interestingly, we found that the promoters of genes involved in T-cell regulation (i.e., CD3D, CD3G, UBASH3A, SIT1, and TXK) were hypermethylated in neonatal sepsis compared to controls, thereby resulting in decreased expression." (PMID 33659006, 2021).
ovarian carcinoma (2 papers, 2023 to 2025). A malignant neoplasm originating from the surface ovarian epithelium. "Nonetheless, the precise role of CD3G in ovarian cancer warrants further investigation." (PMID 37284314, 2023).
prostate tumors (2 papers, 2018 to 2022). "Eventually, under the overexpression of target gene CD3G, this indirectly results in the chronic inflammation of prostate tumors." (PMID 35164166, 2022).